RNU6-1099P (RNA, U6 small nuclear 1099, pseudogene)
Gene: Small nuclear RNA gene on chromosome 1 (19,305,076 to 19,305,182, reverse strand). Ensembl gene ENSG00000200403.
Homologues: Orthologues: chimpanzee U6 (96% identical). Paralogues in human: RNU6-16P (93% identical), RNU6-29P (93% identical), RNU6-1 (92% identical), RNU6-19P (92% identical), RNU6-2 (92% identical), RNU6-39P (92% identical), RNU6-3P (92% identical), RNU6-4P (92% identical), RNU6-5P (92% identical), RNU6-6P (92% identical), RNU6-9 (92% identical), RNU6-12P (91% identical), and 1287 more.